CXCL8 (C-X-C motif chemokine ligand 8)
Diseases named in the same sentence as CXCL8 in open-access papers (continued):
Sharing a sentence is not in itself a finding about the gene and the disease.
COVID-19 (continued). "Similarly, activation of COX2 and HIF-1α in COVID-19 has been shown to upregulate the antiapoptotic antiproliferative microenvironment (BCL2, BNIP3) and M1 immune system {nuclear factor kappa B (NFKB), Egl-9 family hypoxia inducible factor 3 (EGLN3), CXCL8, TNF-α, and IL-6 }." (PMID 36671699, 2022). "Indeed, defined circulating factors - CXCL8, IL-10, IL-15, IL-27, and TNF-α - positively correlate with older age, longer hospitalization, and a more severe form of the disease and may thus represent the leading signature in critical COVID-19 patients." (PMID 33159040, 2020). "Non-severe COVID-19 cases showed an increase in IL1β, IL-6, IL-10 and TNF and severely ill patients had higher levels of the cytokines IL-6, IL-10 and CXCL8." (PMID 37515295, 2023). "Of note, CXCL5, CXCL8 and CCL25, which correspond to the chemokine antibodies representing the COVID-19 hospitalization signature, were not significantly different between mild and severe hospitalized COVID-19 convalescents in the Milan cohort." (PMID 36879067, 2023). "Antibodies against CXCL5, CXCL8 and CCL25 were all lower in previously hospitalized compared with outpatient COVID-19 convalescents, and this was not linked to the therapy received during hospitalization." (PMID 36879067, 2023). "In the COVID-19 hospitalization signature, antibodies to CXCL5 and CXCL8 were negatively correlated with RBD IgG and age, but not with sex." (PMID 36879067, 2023). "On the other hand, some markers (i.e., IL-5, IL-7, IL-17A, CXCL8, and VEGF) were increased in critical COVID-19 patients only and not in macrophage activation syndrome." (PMID 35645351, 2022). "Unlike increased levels of TNFα, IL-6, IL-8, IL-10, CXCL8, and IP-10 observed in H1N1 infected pregnant patients, COVID-19 pregnant patients showed relatively lower expressions of pro-inflammatory and anti-inflammatory cytokines." (PMID 34012458, 2021). "We conclude that the observed upregulation of IL1B, CXCL8 and CCL3 in week 2 compared to the later time points is attributable to interindividual patient differences rather than a general feature of convalescent COVID-19 patients." (PMID 38391913, 2024). "The ongoing inflammatory response after acute COVID-19 remission keeps the expression of proinflammatory cytokines such as IFN-β, IFN-λ1, IFN-γ, IL-2, IL-6, IL-17, CXCL8, CXCL9, and CXC10 upregulated, the activation of non-classical and intermediate monocytes, fibroblasts, and myeloid cells." (PMID 38097988, 2023). "Concentrations of select chemokines (CXCL8, CXCL10, CCL2, CCL3, CCR1) and complement factors (C2, C9, CFD, C4BPA, C5AR1, CR1) were examined at mRNA and protein levels with regard to a COVID-19 course (ICU vs. non-ICU group) and CMV status at different time intervals." (PMID 36232655, 2022). "We also identified 35 drugs targeting ALPL, CXCL8, and IL6 that were not previously tested against COVID-19 symptoms and could be repurposed for anti-SARS-CoV-2 management." (PMID 34582497, 2021).
breast carcinoma (791 papers, 2004 to 2026). "Previous analyses have reported that CXCL8 expression was negatively correlated with Erα expression and linked to increased invasiveness potential of breast cancer." (PMID 37940972, 2023). "In light of our results, CXCL8 appears to provide the most improvements in the diagnostic process of breast cancer as a single parameter, as well as when combined with CA 15-3, but our study needs to be expanded." (PMID 36431173, 2022). "The highest values of diagnostic power were observed for CXCL8, both in the total study group and in luminal subtype B of breast cancer." (PMID 36431173, 2022). "Higher CXCL8 mRNA levels in breast cancer tissues were associated with significantly shorter overall survival." (PMID 36431173, 2022). "In the present study, we investigated the plasma concentrations of CXCL1 and CXCL8 in female breast cancer patients as potential tumor markers in the diagnostic process, as an individual or combined parameter with the routinely used marker CA 15-3." (PMID 36431173, 2022). "Ataxia-telangiectasia mutated (ATM) protein kinase regulates CXCL8 to enhance cell migration, invasion, and metastasis in breast cancer." (PMID 35011369, 2021). "CXCL8 was also up-regulated in TNBC co-cultures with breast cancer-associated fibroblasts (CAFs) derived from patients." (PMID 31031757, 2019). "In breast cancer patients, CXCL8 overexpression was observed in tumor tissues and associated with bone metastasis." (PMID 28883082, 2017). "CXCL8 was reported to be associated with tumor progression in breast cancer, colorectal cancer, non-small cell lung cancer, gastric cancer and melanoma." (PMID 29285315, 2017). "It is evident that CCL2 (MCP-1), CCL5 (RANTES), and CXCL8 (IL-8) have pro-malignant activity that is associated with breast cancer progression and more advanced disease." (PMID 24260134, 2013). "Interestingly, we identified many TNF-α pathway genes to associate significantly more strongly with CXCL8 when comparing breast cancer cell lines with the entire dataset (p = 0.02, paired t test)." (PMID 40833805, 2025). "Additionally, the positive correlation we measured between CXCL8 and a number of TGF-β1 and TNF-α–associated genes in a large dataset of breast cancer cell lines validates our in vitro findings on a positive regulation of CXCL8 by TGF-β1 and TNF-α." (PMID 40833805, 2025). "According to these results, CXCL8 may be a useful diagnostic marker for breast cancer, which we also investigated in a different paper." (PMID 37370728, 2023). "Nevertheless, we are the first group, to our knowledge, to analyze the diagnostic utility of CXCL1 and CXCL8 in breast cancer, in combination with CA 15-3, and we hope that our research will inspire other researchers and prove to be useful in the diagnostic process in the future." (PMID 36431173, 2022). "Furthermore, CXCR2 and several of its ligands (CXCL1, CXCL2, CXCL5, CXCL7 and CXCL8) have also been linked to breast cancer progression and metastatic invasion." (PMID 32581213, 2020). "Interestingly, an association of CXCL8 and miR-146a-5p was found in breast cancer cells and senescent human fibroblasts." (PMID 26859141, 2016). "Furthermore, functional single-nucleotide polymorphisms (SNPs) located in the promoter region of CCL2 and CXCL8, and thus regulating transcription of these chemokines, have been associated with clinical breast cancer outcome." (PMID 24260134, 2013). "Specifically, we observed significant associations between CXCL8 and TNF-α genes in breast cancer cell lines." (PMID 40833805, 2025). "Elevated CXCL8 levels have been reported in a wide range of cancers, including colorectal, pancreatic, and breast cancers, where it promotes tumor growth, metastasis, and resistance to therapy." (PMID 40087784, 2025). "Their recruitment to the TME, mediated by chemokines such as CXCL1 and CXCL8, and their subsequent activation underscore their complex role in breast cancer biology." (PMID 40486614, 2025).
breast carcinoma (continued). "We noted elevated pro-inflammatory activity interactions, specifically with CXCL1, CXCL2, and CXCL8 in primary breast cancer." (PMID 40858590, 2025). "CDK2, PCNA, CXCL8, and E2F1 were involved in the cell cycle, and were associated with worse survival for breast cancer." (PMID 40697521, 2025). "CAAs are defined as high producers of CXCL8, CCL2, and IL-6 associated with breast cancer development." (PMID 40076892, 2025). "Breast cancer tumorspheres presented a statistically significant increase in CXCL8, IL6, IL6R, and NFKB1 mRNA levels in comparison to adherent cell culture, while TGFB1 mRNA expression was decreased." (PMID 39336151, 2024). "CXCL8 expression has varied by breast cancer stage (p = 0.00561) and is higher in metastatic tissues and grade 3 tumor cells than in grade 1 and 2 tumor cells (p < 0.05; p < 0.0001)." (PMID 37370728, 2023). "At the same time, CXCL8/IL-8 appears to be more important in the formation of bone metastasis of breast cancer than CXCL1." (PMID 37108425, 2023). "This article summarizes existing knowledge about the roles of CXCL ELR-positive chemokines CXCL1, CXCL2, CXCL3, CXCL5, CXCL6, CXCL7, and CXCL8 as peripheral blood and tissue markers in the diagnosis and prognosis of women with breast cancer." (PMID 37370728, 2023). "Breast cancer cells secrete CXCL1 and CXCL8/IL-8, resulting in the chemotaxis of neutrophils into breast cancer cells." (PMID 37108425, 2023). "Independent breast cancer cohort GSE20685 dataset showed that higher CXCL8 predicted worse survival." (PMID 37898619, 2023). "In breast cancer, two human cell lines were shown to each produce a different isoform of CXCL8 with a difference in potency between the two." (PMID 37025604, 2023). "IL-1 activates downstream pathways including NF-kB which increases the migratory activity of breast cancer cells, and in turn upregulates CXCL8 under oxygen deprivation." (PMID 37065483, 2023). "CXCL8 concentration differentiated a group of breast cancer patients from healthy controls with 95.6% sensitivity, 95% specificity, and a diagnostic test power equal to AUC = 0.998." (PMID 37370728, 2023). "It was relatively recent (in the early 2000s) that researchers noticed the increased expression of CXCL8 in the blood of patients with breast cancer." (PMID 36831112, 2023). "The tissue expression of CXCL8 protein was higher in breast cancer than in healthy tissues (p < 0.05)." (PMID 37370728, 2023). "Based on the results of binary logistic regression analysis, they found that serum CXCL8 concentration was a predictor of differentiation between the benign lesion group (p = 0.024), breast cancer group (p = 0.011), and healthy controls." (PMID 37370728, 2023). "Depending on the source, CXCL8 mRNA in breast cancer is overexpressed (p < 0.05), underexpressed (p < 0.001), or not differentially expressed in healthy tissue." (PMID 37370728, 2023). "Accumulated evidence has revealed that CXCL8 promotes metastasis in many tumors, such as thyroid cancer, prostate cancer, GC, and breast cancer." (PMID 35321317, 2022). "Many studies have proved that CXCL8 can promote cell proliferation and inhibit apoptosis in multiple cancers, including breast cancer, prostate cancer, lung cancer, colon cancer and so on." (PMID 35372515, 2022). "Compared with normal breast tissue, significantly elevated mRNA levels of CXCR2 and LIF in breast cancer-associated adipocytes, and the expression of CXCL1-3, and CXCL8 in breast cancer tissue were up-regulated." (PMID 35280694, 2022). "Our RNA-seq results showed that the expression of CXCL1, CXCL2, CXCL3, and CXCL8 was significantly increased in breast cancer cells after co-culturing with adipocytes." (PMID 35280694, 2022). "An abnormal expression of CXCL1 and CXCL8 has been found in many types of malignancies, including breast cancer." (PMID 36431173, 2022).
breast carcinoma (continued). "Combined with RNA-seq analysis, we found that CXCL1-3 and CXCL8 are highly expressed in co-cultured breast cancer cells, and CXCR2 is the critical receptor to activate the ERK1/2 signaling pathway in CAAs." (PMID 35280694, 2022). "CXCL8 regulates the biological functions in various cancers, such as breast cancer, prostate cancer, osteosarcoma, and colorectal carcinoma." (PMID 36290882, 2022). "Expression of CXCL8 transcripts and protein abundance were assessed in human breast cancer cell lines in which we blocked SHP2 using shRNA constructs or an allosteric inhibitor." (PMID 35739379, 2022). "For example, in melanoma and breast cancer, CXCL8 overexpression plays a key role in metastasis and poor patient survival outcomes." (PMID 36072669, 2022). "Other metastases genes associated with poor prognosis in breast cancer, such as CEACAM6, COL17A1, CXCL8, TNFAIP3, SEMA7A and L1CAM, are also attenuated with SP receptor antagonist treatment." (PMID 34359773, 2021). "These CAFs secrete prometastatic chemokines including CXCL6 and CXCL8 in Luminal-A breast cancer cells and enhance migration." (PMID 35011369, 2021). "We examined CXCL protein levels through IHC and found that the protein expressions of CXCL8 and 10 were statistically significantly up-regulated in human breast cancer, pancreatic cancer, and colon cancer tissues versus the corresponding normal samples." (PMID 34439306, 2021). "Elevated CCL5 (RANTES), CCL2 (MCP-1), and CXCL8 (IL-8) in TNFα/IL-1β primed triple-negative subtype of breast cancer cells (TNBCs): hBMMSCs co-cultures increase BCC lung metastases." (PMID 33849537, 2021). "The findings indicate the involvement of polymorphisms of the IL-6, C-X-C motif chemokine ligand 8 (CXCL8), and TNF genes and modification of methylation in the TNF gene promoter favoring the occurrence of chronic breast pain after breast cancer surgery." (PMID 34685397, 2021). "The stemness of the breast cancer cell line MCF-7 was increased after CXCL8 stimulation in a tumorsphere-formation assay." (PMID 35011369, 2021). "Activated hepatic stellate cells secrete CXCL8 to induce the proliferation of breast cancer cells and stimulate dormant cancer cells to grow in a 3D liver microphysiological system." (PMID 35011369, 2021). "CXCR2 and CXCL8 regulate breast cancer progression in the TME by modulating several related pathological processes, including promoting breast cancer growth, angiogenesis, invasion, metastasis, and reducing cancer cell sensitivity to chemotherapy." (PMID 33747948, 2021). "CXCL8 mediate the initiation and development of various cancers, such as breast cancer, prostate cancer, lung cancer, colorectal carcinoma, and melanoma." (PMID 33190424, 2021). "CXCR1, one of the receptors for CXCL8, has been identified as a druggable target on breast cancer cancer stem cells (CSC)." (PMID 34476645, 2021). "Sulconazole inhibits breast cancer cell proliferation and cancer stem cell formation via the NF-κB/CXCL8 signaling pathway." (PMID 35011369, 2021). "A recent study showed that danirixin suppressed breast cancer migration, invasion, and metastasis mediated by CXCL8 and TAMs." (PMID 35011369, 2021). "In breast cancer, CXCL8 promotes cancer cell stemness, which increases cells’ ability to grow as spheres in suspension culture (3D)." (PMID 34725321, 2021). "It has been reported that CXCL8 and its cognate receptors facilitate the onset and progression of various types of cancers including melanoma, breast cancer, colorectal cancer, lung cancer, and prostate cancer." (PMID 33585006, 2020). "CXCL8 (C-X-C motif chemokine ligand 8) is correlated with clinical breast cancer stage and lymph node metastasis." (PMID 33378415, 2020). "It has also been indicated that a higher level of CXCL8 promotes the invasive capacity of breast cancer cells." (PMID 33378415, 2020).
breast carcinoma (continued). "With relevance to obesity-related aspects of breast cancer, CXCL8 that was induced via the PI3K/Akt-mediated pathway was found to mediate the EMT-inducing effects of leptin and its ability to increase tumor cell invasion." (PMID 32582148, 2020). "Along these lines, CXCL1 as well as CXCL8 have been found to promote the proliferation of breast cancer cells." (PMID 32582148, 2020). "Further evidence on the connection between CXCL8 signalling pathway and YAP/TAZ was found in breast cancer cell lines, where YAP inhibition was associated with a low amount of CXCL8 secretion." (PMID 31986121, 2020). "We have previously shown that the ligands of human chemokine receptor CXCR2 (CXCL1, CXCl2, CXCL3, CXCL5, CXCL6, CXCL7 and CXCL8) were coregulated in breast cancers, presumably because of their common location in a narrow region of chromosome 4q." (PMID 32727083, 2020). "Using a cohort of breast cancer patients for which we had obtained data on multiple cytokines, including CXCL8 as well as immune infiltration, we have first performed an extensive review of available CXCR2 Ab, as CXCR2 immunostaining remains controversial." (PMID 32727083, 2020). "Studies show that CXC chemokine ligand 8 (CXCL8 or IL-8) promotes the EMT of human breast cancer cells via the formation of the TWIST1-p65 complex that activates transcription of NF-κB and increases the binding affinity of p65 to CXCL8." (PMID 31430935, 2019). "CXCL8 has been reported to promote tumor cell growth, induce migration of melanoma and breast carcinoma cells, and stimulate angiogenesis." (PMID 31885609, 2019). "Second, in breast cancer patients with pleural effusions and/or ascites CXCL8 levels were measured and tumor cells recovered and cultured in vitro." (PMID 30788286, 2019). "A CXCR2 ligand, CXCL8, has been shown to be an important player in osteoclast activation and bone metastasis in breast cancer." (PMID 30871004, 2019). "CXCL8 has been determined to be involved in a multiple of cancers, such as breast cancer, prostate cancer, lung cancer, and melanoma." (PMID 31304688, 2019). "More specifically, the bone-tropic subclone MDA-MET derived from the human breast cancer cell-line MDA-MB-231 was found to secrete high levels of CXCL8." (PMID 31572390, 2019). "Chemokines such as CCL2, CCL5, CCL4, and CXCL8 are also involved in the incidence and development of breast cancer." (PMID 31398937, 2019). "Compared with healthy volunteers, patients with breast cancer have elevated levels of CXCL8, and the severity of this overexpression is positively correlated with disease stage." (PMID 31788042, 2019). "CXCR2 affects angiogenesis in breast cancer primarily by interacting with CXCL8 and CXCL1, however the specific mechanism is yet to be determined." (PMID 31788042, 2019). "Although CXCL8 is the most commonly studied ligand of CXCR2 in breast cancer, other CXCR2 receptor agonists, such as GRO-α, GRO-β, GRO-γ and CXCL5, are co-regulated with CXCL8." (PMID 31788042, 2019). "The combination of these 16 IgG genes with CXCL8 has been suggested as a prognostic marker in breast cancer in general; we, therefore, examined expression of this metagene in our TNBC cohort." (PMID 29899747, 2018). "The administration of dehydroepiandrosterone, an adrenal hormone with a protective role against cancer, inhibited the secretion of several chemokines including CXCL8, which was paralleled by a reduction of breast cancer cells growth." (PMID 29977225, 2018). "In previous study, we found that DACH1 restrained CXCL8-induced invasion and metastasis of breast cancer through selectively interacting with the AP-1 and NF-κB binding sites of the CXCL8 promoter." (PMID 29636079, 2018). "Reparixin is an allosteric inhibitor of IL-8 (CXCL8) receptor CXCR1/2 has the activity against BCSCs in xenografts of breast cancer." (PMID 30175384, 2018).